IL33 (interleukin 33)
Diseases named in the same sentence as IL33 in open-access papers (continued):
Sharing a sentence is not in itself a finding about the gene and the disease.
infection (continued). "However, because Mφ alternative activation can occur independently of IL4R via FcR ligation or other polarising signals such as IL-33, we do not rule out a role for Mφ alternative activation signals being triggered by non-lymphocyte, IL-4 responsive cell types in our infection system." (PMID 29547639, 2018). "However, there was a significant decrease in the total lung concentration of IL-13 in the RSV-infected IL-33 KO mice compared with RSV-infected WT mice (Fig E5, D), highlighting an equivocal role for IL-33 during RSV-induced ILC2 activation in our murine model of infection." (PMID 27156176, 2016). "To investigate how IL-33 might interfer with the host immune response, we measured the levels of the key Th1 cytokines (IFN-γ, IL-12 and TNF-α), key Th2 cytokines (IL-4, IL-5 and IL-13), and the regulatory cytokine IL-10 in the serum at various time-points after infection with PbA." (PMID 25659095, 2015). "These Th2 cells display innate-like functionality and respond to secondary infection in an antigen-independent, ST2/IL-33-dependent manner, indicating that protection is not due to conserved antigens." (PMID 38277692, 2024). "While most genes showed no significant change in expression upon infection, a few patterns emerged: TBX21 and IL-4 were slightly under-expressed in infected cells, while IL-33 was slightly over-expressed." (PMID 39273061, 2024). "However, it may not be the sole transcription factor for IL-33 production in infection." (PMID 38750790, 2024). "IL-33, IL-27, and TIMP-1 were lower than the limit of detection or showed no significant change from the mock infection model on both sides (data not shown)." (PMID 37725516, 2023). "Infection with Hp did not modulate the levels of mRNA for UCP1, IL33 or PPARγ in EWAT of HFD-treated animals at 5 weeks post infection suggesting a minor role of these factors in Hp-associated weight control." (PMID 35499991, 2022). "Absence of the IL-33/ST2 axis enhanced the expression of inflammatory cytokines, but not TH1 or TH2 cytokines, in the air pouch after infection." (PMID 34638904, 2021). "The authors found multiple alarmins (HMGB1, IL-33, S100A8, and S100A9) in the joint capsule of the FS patient group in amounts consistent with an infection, while in the control group they found no significant increase of infection related markers." (PMID 34046418, 2021). "As for IL-33, an ST2-binding cytokine, we observed that in ST2−/− mice the production of this cytokine was already naturally decreased and after infection there was no change in this profile when compared to the WT mice." (PMID 32353980, 2020). "In summary, we provide evidence for a non-redundant IL-33-triggered ILC2-, IL-9-, and mast cell-dependent innate pathway facilitating the defense against intestinal helminths during the first week of infection." (PMID 33351862, 2020). "To characterize the activation and differentiation states of CD8+ T cells primed without IL-33 signals, we infected WT and Il1rl1−/− mice with LCMV and analyzed their CTLs at day 6.5 after infection." (PMID 31447845, 2019). "In nonpolarized macrophages, this enhancement of infection by JEV was statistically significant for IL-33 alone, for IL-33 combined with TSLP, and for IL-33 combined with TSLP and IL-25." (PMID 30282716, 2018). "The cytopathic effect (syncytia and lysis of monolayer cells) appeared from day 3 PI (data not shown) and a significant increase of mRNA expression of IL-33 was observed at day 4 and day 5 of L2-MHV3 infection." (PMID 28607531, 2017). "Nonetheless, the absence of IFNγ induction in IL-33 KO and the expressions of CXCL10 and CXCL11 were strongly upregulated during L2-MHV3 infection especially in IL-33 KO background at 72 h PI." (PMID 28607531, 2017).
infection (continued). "Furthermore, P4-treatment did not activate markers of ILC2s, including IL-13 and IL-33 production, or increase numbers of Tregs in the lungs during infection, suggesting that the induction of AREG in response to P4 may not be occurring in these immune cell populations." (PMID 27631986, 2016). "Immunity could not be induced by IL‐33 administration in SCID mice lacking T and B cells, affirming that T cells rather than ILC2s are the likely drivers of immunity during HD Tm infection, as noted in IL‐25 administration." (PMID 40944312, 2025). "Even though the absence of IL-33/ST2 signaling or ILC2s in full knockout (KO) mice improved HSC function and reduced the myeloid-skewing in aged animals, this does not necessarily lead to an improved immune control against infections in these animals." (PMID 40384929, 2025). "The IL-33 concentrations were significantly higher in CF subjects than in non-CF subjects, while the HMGB1 concentrations were higher in non-CF controls with repeated infections." (PMID 36675299, 2023). "Within the first 5 days of infection, the absolute numbers of ILC2 did not significantly change in the dermis, which is in line with the unaltered expression of cytokines activating (IL-18, IL-25, IL-33, TSLP) or inhibiting ILC2 (IL-27, IFN-γ)." (PMID 35894051, 2022). "In this report, we demonstrate that infection-triggered IL-33 release results in thymic involution-mediated T cell aging in an ST2-dependent manner, suggesting that IL-33 functions as a cytokine, rather than an intracellular nuclear transcriptional regulator, to cause thymic involution." (PMID 36371464, 2022). "However, there was a significant effect of infection on both TFF2 (F = 3.23 p = 0.015) and TFF3 after transformation (F = 12.04, p <0.0001), but not on IL-33 levels after transformation (F = 1.88 p = 0.1031)." (PMID 34662329, 2021). "Unlike conventional cytokines, IL-33 is typically released by epithelial cells following damage to barrier tissue and binds to ST2 that forms a heterodimer with IL-1RAcP to serve as an alarmin in response to inflammation and infection." (PMID 34194431, 2021). "Infection with SA-induced or PA-induced high production of IL-1β, IL-23, and TGF-β in nasal epithelial cells, whereas no IL-33 or TSLP could be detected." (PMID 31089134, 2019). "Similar to the IL-33 treatment model, endogenous IL-33 protection was not restricted to binary toxin expressing strains as only 40% of ST2−/− mice survived attenuated R20291_cdtb infection, compared with 100% of wild-type mice." (PMID 31221971, 2019). "In addition, contact with Pseudomonas aeruginosa has been reported to stimulate IL-33 but not HMGB1 expression, and this finding might correlate this infection with an increased Th2 reaction." (PMID 36675299, 2023). "RT-qPCR for the viral genome showed IL-33 significantly increased HRV16 replication, which was paralleled by a significant rise in the release of infectious virus particles as determined by TCID50 assay suggesting that rather than being protective, IL-33 promotes the infection of MCs by HRV16." (PMID 36366528, 2022). "The absence of IL-33 (or IL-33 signaling via knockout of its receptor) completely abolished the severe RSV disease phenotype in neonatal mice; while the administration of the cytokine during infection in adult mice resulted in exacerbated Th2 inflammation, lung dysfunction, and airway mucus." (PMID 26473724, 2015). "Interestingly, another infection-induced anti-inflammatory cytokine transforming growth factor-beta (TGF-β) was not affected upon IL-33 neutralization, suggesting that TGF-β may not be under the control of the IL-33 pathway." (PMID 38750790, 2024).
cancer (299 papers, 2012 to 2026). A tumor composed of atypical neoplastic, often pleomorphic cells that invade other tissues. "Alongside this axis, some studies suggest the complex interaction between IL-33 and IL-4 that has a well-established regulatory role in the cancer microenvironment associated with cell survival, proliferation, and metastasis." (PMID 40943444, 2025). "In head and neck squamous cell carcinoma, cancer-associated fibroblasts were found to release IL-33, which in turn led to migration and invasion through epithelial-mesenchymal transition." (PMID 39911848, 2025). "IL-33, primarily located in the stroma, demonstrates enhanced expression within carcinoma-associated fibroblasts (CAFs)." (PMID 40196136, 2025). "IL-33 has been detected in cancer-associated fibroblasts (CAFs) and is a critical mediator in CAF-induced invasiveness." (PMID 38662248, 2024). "Our analysis did not reveal any significant associations between the levels of IL8 and IL33 in cancer patients." (PMID 38398137, 2024). "In the context of cancer, Il-33 is linked to using eosinophils for antitumor effects, such as inhibiting growth and preventing metastasis." (PMID 40236667, 2024). "A previous study has shown that the high expression of IL-33 in both cancer cells and stromal CAFs is associated with better two-year survival of patients with BTC." (PMID 38509504, 2024). "In breast cancer, IL-33 secreted by cancer-associated fibroblasts enhances ILC2 and Th2 type responses, induces the TCR-independent secretion of IL-13, and recruits immunosuppressive granulocytes." (PMID 40236667, 2024). "Elevated IL-33 levels are associated with conditions such as asthma, inflammatory bowel disease, cardiovascular disorders, and certain cancers, making it a significant biomarker and therapeutic target." (PMID 39149516, 2024). "Mechanistically, IL-33 can promote metastasis via the induction of desmoplastic reactions by activating cancer-associated fibroblasts." (PMID 37455828, 2023). "Conversely, 28 pathways in the KO_IL-25/IL-33 transcriptomes were associated with cytokine–cytokine receptor interaction, pathway in cancer, glutathione metabolism, purine, and pyrimidine as well as Ras/Rap1 signaling." (PMID 37337050, 2023). "Andreone and colleagues underline the central role of IL-33 through in vitro experiments where induction of eosinophil degranulation by IL-33 in the context of cancer is even superior to that of IL-5." (PMID 35563461, 2022). "IL33 was previously associated to prognosis in other cancers and it is known to have pro- and anti-tumorigenic properties mediated through immune cells." (PMID 36536332, 2022). "Aberrant expression of IL-33 and its receptors has been described for multiple types of cancer, and has also been linked to increased malignancy and worse prognoses." (PMID 35409061, 2022). "The LC-LK CCPs are made of two or three nodes maximum and identified four genes (SNRK, BIRC5, HBB, and IL33) associated with the acquisition of the hallmarks of cancer." (PMID 36101460, 2022). "ReactomeFIViz enrichment analysis in Cytoscape showed that four genes (SNRK, BIRC5, HBB, and IL33) have evidence of their association with the acquisition of cancer characteristics." (PMID 36101460, 2022). "We confirmed previously that carcinoma-associated fibroblasts (CAF)-induced interleukin-33 (IL-33) contributed to cancer progression." (PMID 34298657, 2021). "Head and neck carcinomas overexpressing IL-33 in cancer cells and carcinoma-associated fibroblasts (CAFs) were characterized by higher invasiveness and worse outcomes." (PMID 34572318, 2021). "Together, these data provide compelling in vitro and in vivo evidence showing novel mechanisms underlying the IL‐33‐macrophage‐MMP‐9 axis‐mediated immune tolerance against cancer cells." (PMID 34486239, 2021). "Cancer-associated fibroblasts produce high levels of IL-33, which act on TAMs and induce their transition from M1 to M2." (PMID 33628592, 2021).
cancer (continued). "Interleukin (IL)-33 is a member of the interleukin (IL)-1 family of cytokines linked to the development of inflammatory conditions and cancer in the gastrointestinal tract." (PMID 34071419, 2021). "There is still a lack of CD44 gene single-nucleotide polymorphisms (SNPs) combined with IL-33/ST2 pathway single-nucleotide polymorphisms in HCC susceptibility analysis literature, although CD44 and IL-33/ST2 have been reported separately in human cancers." (PMID 33062675, 2020). "Kaplan-Meier analysis revealed that IL-33 levels solely in cancer cells were significantly associated with 2-year survivals (P = 0.027) but not statistically significant in 5-year survivals." (PMID 33046978, 2020). "In this study, IL-33 level was investigated in cancer cells and stromal cancer-associated fibroblasts (CAFs) of clinical human intrahepatic CCA samples." (PMID 33046978, 2020). "Pathogenic activation of IL-33/ST2 signaling also occurs in cancer and is associated with an increase in immunosuppressive cell types and increased M2 macrophages." (PMID 32098318, 2020). "Interleukin (IL)-33 is a danger-associated signal that can serve as a molecular alarmin when released upon necroptotic and necrotic cell death including death of cancer cells." (PMID 31227713, 2019). "In head-and-neck-squamous cancers, cancer associated fibroblasts was found releasing IL-33, sequentially leading migration and invasion through epithelial-to-mesenchymal transition." (PMID 30619376, 2018). "It has been established that the expression level of IL-33 is associated with poor prognosis and predicts unresponsiveness to chemotherapy in certain cancers, including CRC." (PMID 30547011, 2018). "It has been recently reported that the expression of IL-33 is associated with clinicopathological variables in certain types of cancers." (PMID 30559604, 2018). "Carcinoma-associated fibroblasts-derived IL-33 promoted cancer cell epithelial-to-mesenchymal transdifferentiation (EMT) to regulate head and neck squamous cell carcinoma invasion and migration." (PMID 30119635, 2018). "In another remarkable study of patients with metastatic colon cancer, higher expression of IL-33 in cancer tissues was significantly associated with poorer survival." (PMID 30619376, 2018). "Recent data revealed the role of IL-33 in several cancers, indicating dual functions as a damage-associated molecular pattern, or nuclear factors mediating gene expression." (PMID 30619376, 2018). "To confirm this clinical association, we further explored IL-33 expression in an independent publically-available cohort of mRNA expression data from 131 cancer specimens obtained at prostatectomy including 19 metastatic tumours." (PMID 27619158, 2016). "The serum concentrations of IL-33 were significantly associated with family history of malignant tumors (p = 0.034)." (PMID 24778632, 2014). "In cancer pain, key ILs implicated include IL-1, IL-6, IL-10, IL-17, IL-18, and IL-33." (PMID 38940936, 2024). "In cancer, IL-33-driven neutrophils are associated with pro-inflammatory and regulatory functions." (PMID 40236667, 2024). "Research has shown that cancer-associated fibroblasts can induce IL-33 production." (PMID 40236667, 2024). "In addition, it has been demonstrated that cancer-associated fibroblast (CAF)–derived IL-33 directly promotes tumorigenesis and metastasis." (PMID 37611111, 2023). "These may underlie the differential roles of IL-33 and IL-25 in different cancer types depending on the tissue site." (PMID 37455828, 2023). "Furthermore, the overexpression of IL-33 has been associated with an enhancement the in cancer stem cell properties commonly linked to resistance to therapy and disease recurrence." (PMID 37762328, 2023). "Thus, we demonstrate that depletion of immunosuppressive TAMs and MDSCs results in decreased TNF-α, causing increased IL-33 levels in carcinoma cells that result in increased cytotoxic T cell response to combat metastatic PDA." (PMID 36256464, 2022).
cancer (continued). "Recent studies have linked IL-33 with the JNK pathway in several cancer types." (PMID 34063627, 2021). "Its role in tumors is under debate; in fact, on the one hand IL-33 can promote T cell antitumor activity, on the other, its expression has been associated with metastasis in several cancer models and, accordingly, it is under study as a therapeutic target." (PMID 34583655, 2021). "In addition to ICB, the IL-33-mediated cancer vaccine has been implicated as an additional option for immunotherapy." (PMID 34209038, 2021). "In particular, IL-33 has the potential to cause inflammation and cancer." (PMID 33308251, 2020). "The results revealed that IL-33 was found in both cancer cells and stromal cancer-associated fibroblast (CAFs) staining patterns which were divided into high (CH) and low level (CL) in cancer cells; and presence (FP) and absence (FA) in CAFs." (PMID 33046978, 2020). "Moreover, increased expression of IL-33 has been associated with cellular growth and proliferation in cancer cells." (PMID 31824476, 2019). "Moreover, studies have also revealed that high expression of IL-33 is associated with disease progression and poor prognosis in diverse cancers." (PMID 30559604, 2018). "High IL-33 expression was also associated with family history of malignant tumor (p = 0.002)." (PMID 24778632, 2014). "Furthermore IL-33 is able to activate NF-κB that has been implicated in the development of several types of human cancers, and is a common transcription factor involved in signaling of several IL-1Family members." (PMID 23062310, 2012). "Besides its role in inflammation, the IL‐33/ST2L axis has been implicated in cancer progression." (PMID 40751595, 2025). "In addition, high IL-33 expression was associated with poor prognosis in cancer patients." (PMID 37507682, 2023). "Moreover, studies have also revealed that high expression of IL-33 is associated with poor prognosis in diverse cancers and may be a potential prognostic predicator." (PMID 30547011, 2018). "Disruptions in the IL-33/ST2L balance have been associated with pathologies such as chronic inflammation, tissue fibrosis, cancer development, and heart failure." (PMID 41614943, 2026). "Interleukin 33 (IL-33) cytokine has been identified as a key initiator of cancer-prone chronic inflammation." (PMID 40647388, 2025). "In short, we demonstrated that during cancer chemotherapy, IL-33 facilitates a DNA damage-resistant TME through different mechanisms." (PMID 40216748, 2025). "We and others have shown that the IL-33/Il1rl1 signaling pathway plays HSCs self-renewal and cancer-promoting roles." (PMID 40659660, 2025). "Interleukin- 33 (IL-33) is an epithelial-derived “alarmin” largely studied in the context of Th2-related immunopathologies and recently implied in cancer immunity." (PMID 40317004, 2025). "Interleukin-33 (IL-33) functions both as a secreted cytokine and as a nuclear factor, with pleiotropic roles in cancer and immunity." (PMID 40040703, 2025). "Our data also suggested that IL-33 displays an opposite expression pattern to JCAD in pathological angiogenesis in human cancer tissues." (PMID 41374934, 2025). "Specifically, the activation of MCs via IL-33 enhances cancer progression and elevates microvessel density (MVD) by recruiting TAMs." (PMID 41425713, 2025). "Recent studies point to the role of the IL-33/sST2 axis as a valuable immunoinflammatory biomarker in cancer." (PMID 40943444, 2025). "The role of IL‐33 in cancer is complex, considering that some studies have shown that it exerts an oncogenic role, whereas other studies have demonstrated the opposite." (PMID 40860436, 2025). "In particular, the activity of IL-31 and IL-33 seems to be crucial in the formation of an immune response against cancers." (PMID 40305195, 2025). "Interleukin-33 (IL-33), a member of the IL-1 family, is an alarmin cytokine that plays an important role in tissue homeostasis and repair, cancer, etc." (PMID 39911848, 2025).